MARCO (macrophage receptor with collagenous structure)
Diseases named in the same sentence as MARCO in open-access papers (continued):
Sharing a sentence is not in itself a finding about the gene and the disease.
tumor (continued). "In line with the phenotypic findings, our observations revealed that the TAMs pretreated with MARCO antibody are capable of activating CD8+ CTLs and inducing substantial tumor cell apoptosis." (PMID 41117057, 2025). "Studies have demonstrated that targeting MARCO with specific antibodies can suppress TAM activation, shift macrophages toward the M1 phenotype, and enhance the effectiveness of anti-tumor immunotherapies in breast, colon cancer, and melanoma models." (PMID 41019045, 2025). "The total proportion of tumor-infiltrated macrophages (CD45+ CD11b+ F4/80+) was decreased in the MARCO-knockout group." (PMID 40695812, 2025). "Collectively, these findings indicate that TAMs rendered immunosuppression by MARCO can impair CD8+ CTL activation and tumor‐killing capabilities." (PMID 41117057, 2025). "Drug delivery systems struggle to penetrate fibrotic tumor regions where lipid‐laden TAMs reside, whereas heterogeneity in SR expression, such as variable CD206 or MARCO levels across metastases, limits nanoparticle precision." (PMID 40904700, 2025). "In contrast, tumour tissue‐enriched C5‐TREM2‐Mφ and C8‐MT1H‐Mφ macrophages displayed a more anti‐inflammatory phenotype, with high expression of genes such as CD163, MARCO, and CSF1R, indicative of an M2‐like phenotype." (PMID 37994257, 2024). "Previous studies have demonstrated that MARCO-high TAMs promote immunosuppressive TME and aggressive tumor phenotypes by enhancing radiation resistance, stemness, and mesenchymal transition." (PMID 39769144, 2024). "In normal tissues, MARCO was expressed at very low levels (<1 TPM) and significantly upregulated in tumor tissue (47-fold increase, p < 0.0001)." (PMID 39457004, 2024). "In contrast, MARCO+ TAM has strong phagocytic ability and can rapidly remove dying tumor cells from the TME, minimizing the accumulation of tumor-derived cGAMP and ATP." (PMID 39464890, 2024). "Tumor-suppressing activity includes the inhibition of tumor angiogenesis (by CD204), tumor invasion (by RAGE), the clearance of tumor cells (by MARCO) and the promotion of M1-like TAM polarization (by CD204 and RAGE)." (PMID 39516356, 2024). "MARCO reduces the infiltration of CD8+T cells and NK cells in PDAC and inhibits effective anti-tumor immunity." (PMID 38590651, 2024). "On the other hand, the expression of many M2 signature genes—including those for FN1, MARCO, MRC1, MSR1, TGF-β1, and TGM2—decreased with tumor progression." (PMID 37441079, 2023). "The anti-tumor functions of TAM-expressing SRs include suppression of tumor angiogenesis (for CD204), tumor invasion (for RAGE), inducing tumor cells clearance (for MARCO) and M1-like TAM polarization (for CD204 and RAGE)." (PMID 36686729, 2022). "In vitro MARCO-expressing TAMs suppressed activation, proliferation and IFNγ production in T cells, resulted in inhibition of T-cell killing activity towards NSCLC tumor cells." (PMID 36686729, 2022). "We determined that MARCO is an independent prognostic factor and that increased MARCO expression in PDAC tissues correlates with poor tumor infiltration of cytotoxic T cells and NK cells." (PMID 36310582, 2022). "Using retrospectively collected tumor specimens and transcriptomic data from PDAC, we demonstrate that expression of the scavenger receptor MARCO correlates with poor prognosis and a lymphocyte-excluding tumor phenotype." (PMID 36310582, 2022). "Of note, MKI67 monocytes and APOE macrophages were mainly derived from tumor, while ADAP2 and MARCO macrophages were mainly from ascites." (PMID 36248860, 2022). "In contrast, CCL18+ macrophages showed a dominant M2-like phenotype with the high expression of CD163, MARCO, and CSF1R, suggesting their stronger tumor-promoting role than SPP1+ macrophages." (PMID 35347134, 2022). "While typical macrophage markers such as CD68, FCGR3A, MARCO, and CD14 were highly expressed in TAMs as well as non-tumor macrophage samples, the expression of canonical M1, M2, and TAM markers was more diverse." (PMID 33918618, 2021).
tumor (continued). "We found that several pro-tumor markers are increased in cancer tissues, including CD163, CD206, SIRPα, LILRB1, SIGLEC10, AXL, MERTK, and MARCO." (PMID 34778091, 2021). "Pairs involving regulation of MARCO, IFITM10, and CD34 appear to function in HCC through changes involving tumor microenvironment and inflammation." (PMID 32228601, 2020). "Multiplex immunofluorescent staining of tumor samples from NSCLC Swedish patients demonstrated the co-localization of CD68, CD163, and MARCO." (PMID 33194645, 2020). "This study showed low expression of MARCO in resting BMDC, with a significant increase following challenge with LPS or tumor lysate." (PMID 25089703, 2014). "Anti-MARCO antibodies have shown tumour-reducing effects across multiple models, although MARCO is also expressed on non-tumour macrophages, highlighting the need for tissue-specific profiling and validation." (PMID 40948757, 2025). "Overall, eleven clusters were identified, of which most were enriched in the tumor, except for a macrophage receptor with collagenous structure (MARCO)+ cluster enriched in the non-tumor liver." (PMID 40507339, 2025). "In addition, MARCO blockade enhanced ICB responses and deterred tumor development in an orthotopic RCC preclinical model." (PMID 41117057, 2025). "MARCO is increased on immunosuppressive TAMs in NSCLC, and if inhibited has been shown to repolarize TAMs facilitating the recovery of cytolytic activity, anti-tumour mediated immunity, and downregulation of Treg activity." (PMID 40385641, 2025). "While we did not see differences regarding the HGPs, no MARCO+ cells have been observed inside the tumor mass." (PMID 39563958, 2024). "M2‐TAMs are tumor‐promoting macrophages and showed high expression of MRC1, CD163, MARCO, and MAF." (PMID 36529697, 2023). "We validated the low expression of MARCO on HB TAMs using FISH, demonstrating the absence of MARCO on CD163+ macrophages in HB tumor tissues." (PMID 36008377, 2022). "Mechanistically, MARCO+ macrophages enhance the proliferative activity of Tregs and IL-10 production as well as reduce CD8+ T cell activity, creating a suppressive microenvironment suitable for tumor cell survival." (PMID 36510315, 2022). "An anti-MARCO mAb was developed and has been shown as having an anti-tumor activity in breast and colon carcinoma, and in melanoma models through reprogramming of TAM populations to a pro-inflammatory phenotype and increasing tumor immunogenicity." (PMID 35163420, 2022). "In NSCLC, early in tumor formation, tissue-resident macrophages displaying the M2-like features, CD206 and MARCO, were shown to promote tumor cell epithelial–mesenchymal transition (EMT), invasiveness and to induce a Treg cell response that limits anticancer adaptive immunity." (PMID 34572013, 2021). "Recently, it was reported that anti-MARCO mAbs suppressed angiogenesis, switched the metabolic program of MARCO+ TAMs, induced NK-cell killing through TNF-related apoptosis-inducing ligand (TRAIL) and synergized with anti-PD-1/PD-L1 mAb therapy, to enhance tumor suppression." (PMID 34638388, 2021). "Interestingly, targeting MARCO by mAbs led to NK cell activation, which in turn increased their TRAIL-dependent tumor cell killing property." (PMID 34572013, 2021). "The mesenchymal expression signature was found primarily in the macrophage population rather than in tumor cells (p < 0.00001, n = 50 patients, Mann-Whitney U test) and specifically within MARCO-expressing macrophages (p = 0.005)." (PMID 34011400, 2021). "Furthermore, we found within our GBM single-cell data that there is significant co-expression of Ki-67 with MARCO (p < 0.00001, n = 17,132 cells, chi-squared test), suggesting that these MARCO+ macrophages may also be proliferating within the tumor microenvironment." (PMID 34011400, 2021).
tumor (continued). "Cluster 0 (THBS1+MHClow TAMs) was prevalent in liver, with high expression of THBS1, MARCO and genes promoting the proliferation of EPCs and angiogenesis, such as EREG, AREG, and VEGFA, which could stimulate tumor growth and progression." (PMID 34489408, 2021). "There was however no significant treatment interaction between MARCO+ and adjuvant chemotherapy (HR = 1.65 95% CI 0.72–3.79 for untreated vs HR = 8.46 95% CI 0.98–73.10, pinteraction = 0.165) in I-type tumours." (PMID 28673320, 2017). "DCs generated from the bone marrow of WT and MARCO-/- mice were unpulsed or pulsed with LPS or tumor lysate (not shown)." (PMID 23840879, 2013). "Medullary sinuses without tumor cells expressed MARCO, but those containing tumor cells in the same LNs lost MARCO expression, despite maintaining expression of the lymphatic identity marker PROX1, indicating that tumor metastasis through the sinuses alters LEC phenotypes." (PMID 41249124, 2025). "Like cytokine-polarized TAMs and MDSCs, we found that tumor-cell-differentiated MARCO+ TCM, independent of cell-to-cell contact, could suppress cytotoxic T cell and NK cell IFNγ production, proliferation, and/or degranulation (CD107a)." (PMID 36310582, 2022). "Our examination of human tumors revealed that T cells and NK cells appeared to be absent in areas positive for MARCO, suggesting that these cells could potentially block entry and activation/migration in the tumor." (PMID 36310582, 2022). "Anti-MARCO mAbs similarly induced TAM re-education towards a pro-inflammatory phenotype in preclinical mouse models of breast and colon carcinoma and melanoma, resulting in increased tumor immunogenicity and tumor growth/metastasis inhibition, and improving the efficacy of checkpoint immunotherapy." (PMID 32456204, 2020). "Interestingly, high MARCO+ expression was significantly higher in tumours with absent vascular growth (p < 0.001) in PB-type tumours." (PMID 28673320, 2017). "Expression of MARCO in MARCO-/- DCs was absent, even after pulsing with tumor lysate or LPS." (PMID 23840879, 2013). "Additionally, MARCO is not expressed on tumor cells itself, so this questions whether tumor cells would be killed effectively when using a MARCO-binding HAdV." (PMID 32957644, 2020). "Despite the lack of ongoing trials of anti-MARCO mAbs, the combination of approaches, whereby both the immune system and specific cancer antigens are targeted, may prove to be a successful mechanism to target specific tumor resident macrophage subsets and to repolarize them." (PMID 36211808, 2022). "Notably, MARCO blockade synergizes with anti-CTLA-4 therapy, but not anti-PD-1, to significantly improve tumor control and survival in murine tumor models." (PMID 41002423, 2025). "SLC28A2, VIP, CMKLR1, MARCO, and NOD2 were detected at low levels in non-tumor and tumor cells." (PMID 38742117, 2024).
infection (43 papers, 2008 to 2025). The state of being infected such as from the introduction of a foreign agent such as serum, vaccine, antigenic substance or organism. "LNs from WT CHIKV but not attenuated CHIKV 181/25–infected mice displayed a reduced and spatially altered expression of Lyve1 by 48 hours after infection as well as a loss of MARCO expression, suggesting that WT CHIKV infection disrupts Lyve1+ LECs." (PMID 38194268, 2024). "For example, mice deficient in SR-A1 are more susceptible to infection with L. monocytogenes, S. aureus, S. pneumonia and N. meningitides, and MARCO-/- mice have enhanced sensitivity to infection with S. pneumonia." (PMID 31596239, 2019). "Whereas our prior results demonstrated that MARCO-deficient mice have increased fungal burden at the early stage of infection, we found that MARCO-deficient mice exhibit decreased pulmonary fungal burden at 35 dpi compared to WT mice." (PMID 29033946, 2017). "Mice with genetic deletions of scavenger receptors, such as SR-A and MARCO, are susceptible to infection or inflammation from inhaled pathogens or dusts." (PMID 18687123, 2008). "However, during the adaptive phase of infection, mice deficient in MARCO have improved fungal clearance which is marker by a type-I skewed immune response." (PMID 29670625, 2018). "MARCO (macrophage receptor with collagenous structure) is a class A scavenger receptor encoded by the MARCO gene, which is constitutively expressed by subsets of macrophages and has been shown to be up-regulated in the presence of infection or in inflammatory conditions in vivo." (PMID 28962035, 2017). "Consistent with our scRNA-Seq analysis, little to no upregulation of these chemokines was observed in WT CHIKV–infected WT or MARCO–/– mice at 8 hours after infection." (PMID 38194268, 2024). "Quantification of LN LEC subsets throughout the acute phase of CHIKV infection revealed reduced numbers of both floor and medullary LECs at later times after infection, and these reductions were MARCO dependent." (PMID 38194268, 2024). "In fact, we identified an increased ratio of CHIKV sgRNA within MARCO+ LECs at 24 hours after infection and both a lower number of expressed host genes and a higher percentage of mitochondrial reads in those cells, suggesting active viral RNA replication." (PMID 38194268, 2024). "By 24 hours after infection, the percentage of inflammatory monocytes remained significantly higher in WT mice than in MARCO–/– mice, although the difference in monocyte numbers was not statistically significant." (PMID 38194268, 2024). "Our analyses indicate that CHIKV RNA accumulates in multiple subsets of MARCO-expressing LN LECs during infection." (PMID 38194268, 2024). "At 8 and 24 hours after infection, Lyve1 and MARCO expression were similar across dLNs from mock-, CHIKV 181/25–, and WT CHIKV–infected mice." (PMID 38194268, 2024). "Concurrent with the lower inflammatory chemokine expression in MARCO–/– mice, we detected less CHIKV RNA in the dLN of MARCO–/– mice at 8 and 12 hours after infection." (PMID 38194268, 2024). "In PRRSV-infected Marc-145 cells, PRRSV GP5 was especially pulled down by the anti-Myc antibody, suggesting an interaction between PRRSV GP5 and MARCO in cases of infection." (PMID 37078873, 2023). "PAMs were infected with recombinant adenovirus to exogenously express MARCO prior to infection with PRRSV at a MOI of 0.5 for various times." (PMID 37078873, 2023). "Upon a PRRSV strain Li11 infection, the mRNA level of MARCO in PAMs was reduced by half at various hours postinfection (hpi)." (PMID 37078873, 2023). "PAMs were infected with PRRSV at a MOI of 0.5 for 24 h after infection with MARCO-WT or MARCO-D recombinant adenovirus." (PMID 37078873, 2023). "The inhibition of apoptosis during infection weakened the inhibition of MARCO on PRRSV, suggesting that MARCO restricts PRRSV infection through the regulation of apoptosis." (PMID 37078873, 2023).
infection (continued). "In contrast, the expression of some inflammation-inducing factors (PPBP, MARCO) was consistently down-regulated in the middle and late stages of infection." (PMID 36338035, 2022). "It has also been suggested that MARCO regulates the activation status of the immune system and can be involved in balancing a proper immune response to infection." (PMID 36078075, 2022). "Studies have demonstrated that MARCO and other scavenger receptors decrease the proinflammatory environment in infections, mediating the clearance of lung pathogens." (PMID 34386467, 2021). "Analogously, infection of MARCO-/- mice with WT CHIKV also resulted in enhanced viremia and more rapid viral dissemination to distal sites, suggesting that the E2 K200R mutation allows the virus to escape from MARCO-dependent clearance." (PMID 31596239, 2019). "Similar to infection of WT mice with CHIKV E2 K200R, infection of MARCO-/- mice with WT CHIKV resulted in an elevated viremia and more rapid viral dissemination to distal sites including the right ankle and quadriceps compared with infection of WT mice." (PMID 31596239, 2019). "MARCO also mediates transduction of macrophages by adenovirus in vitro, and appears to promote innate immune responses to the infection, suggesting that MARCO-virus interactions can regulate host cell responses to infection." (PMID 31596239, 2019). "Mechanisms underlying increased susceptibility to secondary infection are many and include deficiencies in bacterial scavenging receptors such as MARCO on macrophages, as well as the depletion of tissue-resident APC populations during primary infection." (PMID 29992170, 2018). "The effects of MARCO in the development of adaptive immunity were less well explored compared to its well-studied innate functions in control of infections such as Mycobacterium tuberculosis, Streptococcus pneumonia, and Leishmania major." (PMID 29033946, 2017). "In this study, we showed that MARCO expression can be later exploited by C. neoformans to modulate T cell polarization during the efferent phase of infection." (PMID 29033946, 2017). "Using an infection model in mice, MARCO has been shown to be important for cytokine and chemokine production in response to S. pneumoniae infection; however, SR-A knock-out mice do not show impaired killing of the bacterium." (PMID 26217337, 2015). "It has been shown that Neisseria meningitidis is a ligand of and mediates host defence against infection through MARCO." (PMID 21299846, 2011). "In vivo study, MARCO expression increased on macrophages in response to infection or inflammatory conditions and this occurs on macrophages that are directly responsive to the stimuli as well as those distal to the initial infectious stimuli." (PMID 21886847, 2011). "Macrophages from MARCO−/− mice also produce markedly lower levels of pro-inflammatory cytokines in response to infection with virulent Mtb." (PMID 19521507, 2009). "Furthermore, we observed numerous CD11b+ cells within the disrupted LN sinuses at 48 hours after infection, and the presence of MARCO contributed to the accumulation of inflammatory monocytes in the dLN." (PMID 38194268, 2024). "Consistent with higher Ccl2 expression in WT mice at 12 and 16 hours after infection, the percentage and total number of inflammatory Ly6Chi monocytes (CD45+CD11c–CD11b+Ly6ChiLy6G–) in the dLN was significantly greater in WT mice at 12 and 16 hours after infection compared with MARCO–/– mice." (PMID 38194268, 2024). "However, by 48 hours after infection, Lyve1 signal was greatly reduced and MARCO signal was undetectable in dLNs from WT CHIKV–infected mice." (PMID 38194268, 2024). "The majority of genes (CTNNB1, MARCO, STAT5a/b, TAP1, and TAP2) that regulate proliferation and differentiation of immune cells showed a differential higher expression in KO and SP-A variants in response to infection." (PMID 32670284, 2020).